IL10 (interleukin 10)
Diseases named in the same sentence as IL10 in open-access papers (continued):
Sharing a sentence is not in itself a finding about the gene and the disease.
tumor (continued). "Tumor-derived exosomes contain TGF-β and IL-10 and release their contents after secretion from cells." (PMID 30477520, 2018). "The mRNA level of IL4 and IL10 was significantly decreased in PKN2-WT tumor cells, but increased in PKN2-K686R tumor cells, indicating that IL4 and IL10 are negatively regulated by PKN2." (PMID 29368606, 2018). "Cytokine levels relative to tumor characteristics were assessed for VEGF, MCP-1, PAI-1, TNF-α, IL-6, transforming growth factor- (TGF-) β, and IL-10 by ELISA at the end of 72 h of coculture." (PMID 30034291, 2018). "It was shown that FasL expression in endothelial cells was cooperatively induced by tumor-derived VEGF-A, IL-10 and PGE2, which allowed endothelial cells to selectively kill effector CD8+ T-cells." (PMID 30477198, 2018). "The miR-214 secreted by various human cancers and mouse tumor models is delivered to recipient Tregs by MVs, efficiently downregulates PTEN, promotes Tregs expansion, and enhances the production of IL-10 in vitro." (PMID 30443251, 2018). "Recent data demonstrated that monoassociation of pks-positivie E. coli increased the tumor burden in gnotobiotic APC(Min/+) mice and APC(Min/+); IL-10(-/-) mice." (PMID 30413188, 2018). "M2 (alternatively activated) macrophages secrete IL-10 and TGF-β and play an active role in tissue remodeling and tumor progression." (PMID 30200478, 2018). "TAMs secrete cytokines, including interleukin-6 (IL-6), interleukin-10 (IL-10), tumor necrosis factor-α (TNF-α), and interferon-γ, which have been shown to promote tumor cell growth." (PMID 30034397, 2018). "IL-10 and IL-4 suppress the local immune response and mediate the recruitment of regulatory T cells and TAM in the tumour microenvironment." (PMID 30539028, 2018). "The increase in Treg cells in the tumor microenvironment results in increased IL-10 and TGF-beta production that stimulates MDSCs, which results in suppression of T cell activation and the promotion of tumor regrowth." (PMID 29862083, 2018). "The tumor promoting functions of TIMs are typically activated by TLR triggering and binding of cytokines and growth factors such as IFN-γ, IL-4, IL-6, IL-10, IL-13, and TGF-β to their responding receptor." (PMID 30233579, 2018). "An example of this is tumor endothelial upregulation of FasL in response to tumor-derived VEGF, IL-10 and prostaglandin E2, which has been shown to selectively kill effector CD8 T-cells but not Treg cells." (PMID 30627131, 2018). "By contrast, TH2-/Treg-like NKT cells produce large amounts of IL-13 and IL-10, respectively, that suppress the TME (i.e., via fibroblasts and MDSC), thereby indirectly stimulating tumor progression." (PMID 29535734, 2018). "Previous studies have shown that tumor-infiltrating (TIL) Tregs substantially upregulate the expression of inhibitory cytokines, such as IL10 and IL35." (PMID 30400822, 2018). "Brain sections harboring the tumor (Vehicle-treated) and scar tissue (CCP-treated and rescued) were triple-stained with Iba1, IL10 and IL12 antibodies." (PMID 30041669, 2018). "The transcription of IL-10 in GAMs is mainly based on STAT3 signaling, which has been shown to be enhanced in tumor-derived GAMs as compared to normal microglia/macrophages." (PMID 29389898, 2018). "The presence of cytokines in the ACP tumours was also assessed by multiplex ELISA against IL1B, IL6, IL8 (CXCL8), IL10, IL18, TNF (TNFα) and IFNG (IFNγ), which revealed the expression of all of these but IFNG in protein lysates from eight human ACPs." (PMID 29541918, 2018). "It is known that Tregs and Bregs can reinforce each other’s pro-tumor phenotype through secretion of TGF-β and IL-10." (PMID 35847834, 2018). "IL-6 is recognized for stimulating tumor growth in GBM patients, whereas IL-10 is known for inhibiting IFN-γ and TNF-α production." (PMID 29651429, 2018).
tumor (continued). "The study further revealed oscillations in the tumor sub-populations in the presence of TH1 derived IFN-γ that eliminates CSC; and the role of IL10 feedback in the regulation of TH1/TH2 ratio." (PMID 30183728, 2018). "We observed that intratumorally inoculated shIL10 LVs transduced tumor and TME-infiltrating cells and reduced the secretion of IL-10." (PMID 29954431, 2018). "In the context of the tumor microenvironment, FASN expression by TAMs polarized cells toward a pro-tumoral phenotype expressing IL-10." (PMID 30619850, 2018). "CAF-educated macrophage progenitor cells reduce T cell proliferation via TGF-β1, IL-10 and ARG1, suggesting that CAFs can induce protumoral TAMs in the tumor immunosuppressive microenvironment." (PMID 29988281, 2018). "One of the functions of the regulatory T-cells is suppressing immune responses in vivo and in vitro directly or via the production of pro-inflammatory cytokines such as IL-10 and TNF which promotes tumor cell growth." (PMID 29849947, 2018). "Tumor cells can also inhibit NK cells and raise CTL cells by regulating the output of VEGF, IL-10, TGF-β, and adenosine ROS immunosuppressive molecules, thus damaging the immune response, and are not recognized by immune cells to escape immune surveillance." (PMID 29552328, 2018). "Following the development of an intraepithelial lesion, this macrophage phenotype is shifted towards an immunosuppressive subset by tumour-derived cytokines as IL4, IL10 and IL13." (PMID 30577495, 2018). "Fourth, secretion of immune inhibitory cytokines (such as IL-10, TGF-β and IL-35) by Tregs can indirectly regulate the role of immune checkpoints in tumor development." (PMID 29735917, 2018). "Tumor samples obtained from ST2KO mice presented lower levels of IFN-γ, TNF-α, IL-10, and IL-17, while the production of IL-12, IL-4, IL-13 and TGF-β was similar between tumor skin samples obtained from wild type and ST2KO mice." (PMID 30112116, 2018). "IL-10 silencing LVs significantly increased the influx of PMN-MDSCs, as well as reduced the number of DCs in tumor." (PMID 29954431, 2018). "We used multiplex ELISA to demonstrate the presence of IL1B, IL6, IL8, IL10, IL18, TNF and IFNG in the cystic fluid and whole ACP tumour protein lysates." (PMID 29541918, 2018). "IL-10 induces infiltration and activation of CD8+ tumor-specific lymphocytes, expression of Th1: IFN-γ cytokines and granzymes, and increases antigen presentation." (PMID 29320562, 2018). "On the other hand, B cells produce IL-10 and TGF-B which inhibit Th1/CD8+ T cells function and promote tumor proliferation." (PMID 29850009, 2018). "The hypoxic tumor microenvironment causes selective up-regulation of PD-L1 on splenic MDSCs and PD-L1 blockade could enhance MDSC-mediated T-cell activation, accompanied by the concomitant down-regulation of immuno-suppressive cytokines IL-6 and IL-10 secreted by MDSCs." (PMID 30619850, 2018). "Although we have reported that IL35+ Tregs support tumor growth by promoting inhibitory receptor (IR) expression in CD8+ TILs, the underlying mechanism of IL35-mediated IR-upregulation and whether and how IL35+ Tregs and IL10+ Tregs cooperatively regulate anti-tumor immunity remain elusive." (PMID 30400822, 2018). "Autologous tumor-specific immune response was seen in two of the three, manifested by IL-5 (1 patient after 3 doses), and IFN-γ, TNF-α, IL-5, IL-10 (after 4 doses in one patient)." (PMID 29258618, 2017). "IL-6 contributes to tumor metastasis via the JAK/Stat3 signaling pathway, and IL-10 phosphorylates of Stat3 in PCNSL cells, while the role of IL-6 in PCNSL remains poorly defined." (PMID 28415725, 2017). "As a member of the IL–10 cytokine family, IL-22 is a potent activator of STAT3, having an important role in tumorigenesis and tumor development." (PMID 28445985, 2017).
tumor (continued). "Thus, the accumulation of M2 macrophages could contribute to the development of an immunosuppressive tumor microenvironment that promotes tumor cell growth, and targeting IL-10–induced M2 macrophage polarization might be a potential therapeutic approach for AITL." (PMID 29100307, 2017). "Cisplatin or carboplatin increased the potency of tumor cell lines to secrete interleukin (IL)-6 and prostaglandin E2 (PGE2) to induce IL-10-producing M2 polarized TAMs." (PMID 28694739, 2017). "Indeed, 20% of these Tetramer+ cells expressed PD-1 in tumor-draining lymph nodes whereas these values increased to 80% in tumor infiltrating T lymphocytes, supporting that in vivo, similarly to IL-10 blockade, inhibition of PD-1/PD-L1 axis would enhance vaccine-induced antitumor T cell responses." (PMID 27926522, 2017). "The alternatively activated M2 macrophages are stimulated by IL4 and IL13, secrete IL10, transforming growth factor-β (TGF-β), and chemokines, and are involved in tissue remodelling and tumour progression." (PMID 29065107, 2017). "Consistent with its effects on cytokine secretion, Reg3g overexpression also reduced tumor expressions of mRNAs for Th1 cytokines IFN-γ and IL-12, and increased mRNAs for Th2 cytokines such as TGF-β and IL-10." (PMID 28880262, 2017). "Other tumour escape mechanisms, such as programmed cell death protein 1 ligand 1 (PDL1) signalling and MDSC/TAM-derived IL-10 immunosuppression, also remain intact." (PMID 28137309, 2017). "In contrast, some studies provide the finding that Th2-derived cytokines (IL-4, IL-5, IL-10, and IL13) show anti-tumor activities in vivo that are as strong as the anti-tumor activities of Th1 cytokines." (PMID 29299026, 2017). "As part of the tumour immunological microenvironment analysis, we determined the relative expression of pro-inflammatory (IL-1β, TNF-α, and IFN-γ), as well as regulatory (IL-10 and TGF-β) cytokines in tumour tissue." (PMID 28874690, 2017). "We observed significantly higher expressions of IL-33, arginase 1, IL-10 and FoxP3 in NSCLC tumor tissues than adjacent tissues." (PMID 28978138, 2017). "TAMs from human neoplasms express arginase 1, interleukin (IL)-10, and transforming growth factor beta (TGF-β); these cytokines reduce the antitumor activity of T cells and natural killer cells, and modulate tumor proliferation, infiltration, and angiogenesis." (PMID 28415741, 2017). "CuB also inhibited IL-10-induced STAT3 phosphorylation, synergistically increasing the anti-tumor activity of Adriamycin in vitro." (PMID 27418139, 2017). "To determine if xenografts of GBM+Pc were able to acquire an anti-inflammatory phenotype in vivo, we analyzed the expression of IL-10 and TGF-β on the tumor/brain edge." (PMID 28978142, 2017). "This in turn promotes IL-10 expression and self-expansion of regulatory CD5+CD19+ B cells (B10) in tumor microenvironment, resulting in promotion of tumor growth." (PMID 29296231, 2017). "The tumor cells themselves can secrete factors that protect them from lysis via CTLs or NK cells or elicit cytokine expression in other cells that enable tumor survival, most notably are TGF-β and IL-10." (PMID 28638385, 2017). "They observed following adoptive transfer into tumor-bearing mice that TH9 cells maintained their IL-9 and IL-10 production in the tumor-draining lung lymph node (LLN) without switching to IFN-γ or IL-17 producers." (PMID 27832300, 2017). "In addition, tumor-infiltrated macrophages could produce IL-10 to promote TAMs self-polarization." (PMID 28241846, 2017). "Serum CCL2, IL-10, IL-5, IL-4, TNF-α, IL1-β and IL-12p70 levels increased with age irrespective of parity status, but were specifically reduced following OC tumor induction only in multiparous mice." (PMID 28966800, 2017). "More importantly, intravenous injection of HCC TEX-pulsed DCs improves the tumor immune microenvironment, in terms of increased T cells and interferon(IFN)-γ levels and decreased IL-10 and TGF-β in tumor sites." (PMID 27713136, 2017).
tumor (continued). "As a potent STAT3 activator, IL-22 is a member of the IL-10 cytokine family, principally produced by Th22 and Th17 subsets of CD4+ T cells which play important roles in tumor development." (PMID 28445985, 2017). "In R2016-treated tumor cells, the secretion of both TGF-β1 and IL-10 was suppressed, suggesting to contribute to the immunogenic anti-tumor effect of R2016." (PMID 28282460, 2017). "In the tumor site of action, TAMs produce cytokines such as IL-10, IL-4, and IL-13 that will act to repair tissues and attract other auxiliary cells that can activate TAM and hence, promoting tumor growth." (PMID 28970834, 2017). "In a preclinical tumor model, ADT also enhances the expression of macrophage-recruiting chemokine CSF1 and M2-promoting cytokines, such as IL13 and IL10 in PCa cells, resulting in more macrophage infiltration and expression of MMP9 and VEGF46." (PMID 29142311, 2017). "In fact, the tumor microenvironment secretes many factors such as GM-CSF, VEGF, SCF, IL-6, IL-10, IL1β, PGE2, cyclooxygenase enzyme (COX) and the complement component C5a which promote recruitment and accumulation of immature MDSCs." (PMID 28609459, 2017). "In the present study, the Th2-class cytokines IL-10, IL-5 and IL4 were also decreased in response to the tumor challenge, but only in multiparous mice." (PMID 28966800, 2017). "TAMs, which in time polarize toward M2 phenotype with poor antigen-presenting capability and immunosuppressive activity by releasing immunosuppressive factors (IL-10, TGF-β, EGF, VEGF, MMPs), are regarded to be pro-tumor for many cells." (PMID 28343267, 2017). "To investigate the contribution of specific cytokines to the proliferation of tumour cells, we performed MTT assays in the presence of neutralizing antibodies to both VEGF-A and IL-10." (PMID 28099146, 2017). "Soluble molecules include cytokines with immunosuppressive activity, such as IL-10, transforming growth factor (TGF)-β, and IL-27, which regulate immune responses to tumor cells and induce T cell dysfunction within the tumor microenvironment." (PMID 28545567, 2017). "We did, however, observe significant changes based on tumor status in inflammatory cytokines (IFN-γ, IL-6, IL-5, IL-2, IL-10) and a growth factor (FGF-basic)." (PMID 27893434, 2017). "Injection of neutralizing anti-IL-4, -IL-10, or -TGF-β1 antibodies can prevent this tumor-induced functional transition, resulting in enhanced CD8+ CTL generation and protection against tumor growth." (PMID 28060744, 2017). "IL-33 neutralization significantly inhibited the expressions of M2 TAM-related genes including arginase 1, IL-10 and VEGF in tumor tissues." (PMID 28978138, 2017). "In this study, vaccination with tumor antigen-loaded DCs plus lenalidomide led to the highest IFN-γ and lowest IL-10 production compared with the PBS control, tumor antigen-loaded-DCs or lenalidomide alone." (PMID 28460478, 2017). "Conversely, M2 macrophages are activated by IL-4, IL-10, and IL-13 and secrete anti-inflammatory cytokines such as TGFβ and IL10, and angiogenic factors such angiopoietin and VEGF, which promote tumor growth, invasion, and metastases." (PMID 28716144, 2017). "Tumour‐derived mediators, such as TGF‐β, IL‐1β and IL‐6, as well as cytokines produced by T cells, such as IFN‐γ, IL‐4 and IL‐10, promote MDSCs population expansion and support their immunosuppressive activity." (PMID 28276625, 2017). "Compared to vehicle treatment, E7046 increased the myeloid cell-derived anti-tumor cytokine TNF-α, and reduced the levels of pro-tumor CXCL1, IL-10, and IL-6." (PMID 28920002, 2017). "This is the first time to show that IL-10 could disturb the actin cytoskeleton of mDCs and deteriorate their biophysical features and motilities, which might be a new aspect of IL-10’s actions on the immune system and represents one of aspects of tumor immune escape." (PMID 28234961, 2017).
tumor (continued). "Two targets, IL-4Rα and cannabinoid receptor 2 (CB2), were validated and confirmed to regulate both IL-6 and IL-10 production in TAMs, contributing to autocrine/paracrine activation of STAT-3 in macrophages and tumour cells." (PMID 28381274, 2017). "Here, IL10 knockout not only decreased JAK1 activity but also inhibited Src phosphorylation, suggesting that IL10 from cancer cells or the tumor microenvironment increases JAK1 and Src activities." (PMID 26956044, 2016). "Use of the anti-Nrp-1 antibody resulted in a significantly augmented number of CD4+TGF-β1+ Th3 cells in the TDLN and tumor tissue and tumor-derived TGF-β1-producing Treg cells from IL10−/− B16/F10 and WT B16/F10 mice." (PMID 27075020, 2016). "Co-treatment also significantly reduced levels of pro-tumorigenic cytokines including TGF-β, VEGF, IL-6, IL-10, and MCP-1 in the ascites while increasing IFN-γ production by CD8+ effector T cells in the tumor ascites." (PMID 27852034, 2016). "BZLF1 also was found to enhance the tumor formation by BZLF1-deleted LCL in SCID mice, through increased expression of IL-6 and IL-10." (PMID 26967558, 2016). "The results showed that expression of TGFβ and IL-10 was significantly upregulated around tumor cells post RT, CT and RCT, indicating high immunosuppression in the tumor microenvironment." (PMID 27389040, 2016). "PAF-R agonists produced in response to UVB/standard chemotherapeutic agents can inhibit tumor immunity via PAF→COX-2→Treg process, which is blocked by antioxidants, COX-2 inhibitors, neutralization of IL-10, and depletion of Tregs." (PMID 26959112, 2016). "Because CDDO-Me enhanced LPS-induced TNF-α secretion, which is associated with M1 activation, we investigated the effect of CDDO-Me on the expression of IL-10 and VEGF, which are tumor-promoting factors produced by TAMs." (PMID 26918785, 2016). "Anti-Nrp-1 not only allowed the increased expansion of tumor-derived CD4+CD8a− T cells, but it also activated tumor-derived CD4+ T cells (CD4+CD69+) in IL-10−/− and WT B16/F10 mice." (PMID 27075020, 2016). "Other factors, such as prostaglandins, interleukin-10 (IL-10), and cyclooxygenase-2 (COX-2) have been described as part of the immunosuppressive tumor microenvironment." (PMID 27294132, 2016). "These molecules include IL-10 and transforming growth factor-β (TGF-β) that are both produced by regulatory T cells (Treg) and other immune and stromal cells in the tumor." (PMID 31051015, 2016). "High HLA-E expression also induces NK cells to secrete IL-10 and TGF-β, which affects the promotion of tumor migration and invasion." (PMID 27322426, 2016). "The cytokines that show elevated expression in human PMP and PDX ascites such as IL6, IP10, IL8, IL10, MCP‐1, and MIP‐1β have all been shown to perform autocrine and paracrine functions and regulate tumor–stromal cross talk." (PMID 26833741, 2016). "IL10 knockout in EGFRL858R and Kras4bG12D mice inhibited the development of lung tumors and decreased the levels of infiltrating M2 macrophages and tumor-promoting Treg lymphocytes." (PMID 26956044, 2016). "FAP reduction decreased transcripts for IL-10, TGF-β, CCL5 and CCL22 from CD14+ cells, of which 20-40% were F4/80+ TAMs; CCL5 transcripts were also reduced in tumor cells." (PMID 26943036, 2016). "In conjunction with NF-κB, β-catenin enhanced expression of immunosuppressive interleukin-10 and suppressed antitumoral CCL3, indicating that β-catenin can induce a favorable tumor microenvironment." (PMID 26776161, 2016). "Peripherally derived Tregs are not believed to be the major population of Tregs in GBM, but presence of IL-10 and TGF-β at high levels in the GBM microenvironment suggests the possibly noticeable role of these cells in immune evasion of the tumor." (PMID 26973839, 2016). "Several tumor-derived immunosuppressive factors have been postulated to play an important role in malignant progression, including VEGF, IL-10, transforming growth factor-beta (TGF-β), prostaglandin E2, and so on." (PMID 27557492, 2016).